USP10 (ubiquitin specific peptidase 10)
Diseases named in the same sentence as USP10 in open-access papers (continued):
Sharing a sentence is not in itself a finding about the gene and the disease.
colorectal cancer (15 papers, 2020 to 2026). A primary or metastatic malignant neoplasm that affects the colon or rectum. "Previously, it has been reported that USP10 loss was linked to lymphovascular invasion and distant metastases in patients with colorectal cancer." (PMID 37919637, 2023). "USP10 has been identified to be involved in metastasis and can drive tumor-associated macrophage polarization in colorectal cancer." (PMID 35433424, 2022). "Thus, the upregulation of USP10 in colorectal cancer is an early event, caused by oncogenic transformation irrespective of genetic driver complexity, and coincides with elevated abundance of the WNT effector β-Catenin." (PMID 39443725, 2024). "In this study, we examined PD-L1 expression in various types of immune cells in human colorectal cancer in connection to cancer progression-specific USPs, including USP10, USP12, USP14, USP18, USP32, USP33, and USP39." (PMID 41356798, 2026). "Since USP10 was not implicated in intestinal homeostasis and β-Catenin signalling, next, we determined expression level of USP10 by interrogating publicly available patient data of colorectal cancer." (PMID 39443725, 2024). "Similarly, in colorectal cancer, USP10 sustains cancer stemness by enabling super-competitor signaling, a mechanism critical for tumor niche dominance." (PMID 41522354, 2026). "USP10 plays an established role in promoting tumor progression in multiple malignancies, such as colorectal cancer, pancreatic ductal adenocarcinoma, osteosarcoma, esophageal squamous cell carcinoma, non-small cell lung cancer, hepatocellular carcinoma, glioblastoma, and prostate cancer." (PMID 41522354, 2026). "In addition, it has also been shown that USP10 is silenced by methylation and downregulated in the early stages of colorectal cancer." (PMID 35627217, 2022). "A recent study showed that USP10 promotes tumor progression and TAM polarization in colorectal cancer." (PMID 35433424, 2022). "Moreover, studies have shown that USP7, USP10, USP33, and USP46 are all involved in the progression of colorectal cancer." (PMID 37371055, 2023).
pancreatic cancer (15 papers, 2016 to 2025). "Upregulated USP10 expression was associated with a worse prognosis in patients with pancreatic cancer." (PMID 37714834, 2023). "However, higher USP10 expression is associated with poorer survival therefore, we assessed its contribution towards pancreatic cancer growth and cellular invasion using the clonal growth and the FITC-based gelatin degradation assays respectively." (PMID 36543867, 2022). "We further confirmed that endogenous DIRAS2 bound to endogenous USP10 in PANC1 pancreatic cancer cells, indicating that the binding is physiologically relevant (bottom)." (PMID 39314885, 2024). "The full rescue of MAPK activation upon USP10 knockdown by DIRAS2 ectopic expression shown in this study indicates that the effect of USP10 on the MAPK signal is mediated by DIRAS2 in pancreatic cancer cells." (PMID 39314885, 2024). "Mechanistically, LINC00460 plays the role of oncogene by acting as a sponge of miR-4689, activating its downstream target, UBE2V1, and sequestering USP10 to promote the proliferation and metastasis of pancreatic cancer." (PMID 37786443, 2023). "Sequencing data from the TCGA database showed an overall increase in USP10 expression in pan-cancer, especially pancreatic cancer, with a 1.1% copy number amplification and gene mutations (data not shown)." (PMID 37714834, 2023). "Immunofluorescence analysis showed that USP10 co-localized with N1ICD in the cytosol of pancreatic cancer cells." (PMID 37714834, 2023). "The role of USP10 in pancreatic cancer is unclear, accordingly, we explored the mechanism by which USP10 regulates its downstream targets in pancreatic cancer." (PMID 37786443, 2023). "Downregulation of USP10 decreased the proliferative and metastatic ability of pancreatic cancer cells." (PMID 37786443, 2023). "Compared to the normal pancreas (GTEx, mean = ~12), the expression of USP10 was higher in the pancreatic cancer cell lines (mean = ~32), and in the pancreatic cancer patient samples (mean for ICGC = ~21, for TCGA = ~15)." (PMID 36543867, 2022). "We find that compared to the normal or malignant stromal tissue, the expression of USP10 is highest in ductal pancreatic cancer tissues." (PMID 36543867, 2022). "We have identified the ubiquitin-specific peptidase 10 (USP10) to play a pro-tumorigenic role in pancreatic cancer." (PMID 36543867, 2022). "Depleting USP10 significantly inhibited clonal growth potential and cellular invasion of pancreatic cancer cells." (PMID 36543867, 2022). "Together these results support a role for USP10 in the pathology of pancreatic cancer and we next sought to determine its functional significance." (PMID 36543867, 2022). "Another microRNA, miR-191, is considered an upstream regulator of USP10 in PDAC (pancreatic cancer) cells." (PMID 35627217, 2022). "Here, we show that USP10 is overexpressed in PDAC patient tissues and K-Ras mutated pancreatic cancer cell lines and higher expression of USP10 was significantly associated with poor overall survival of PDAC patients." (PMID 36543867, 2022). "Phenotypically, silencing USP10 decreased viability, clonal growth and invasive properties of pancreatic cancer cells." (PMID 36543867, 2022).
pancreatic cancer (continued). "Previous studies have indicated that in esophageal squamous cell carcinoma, PABPC1 fosters both angiogenesis and malignant progression by inducing IFI27 mRNA stability, and PABPC1 de‐ubiquitinated by USP10 promotes the stability of CLK2 mRNA to facilitate the development of pancreatic cancer." (PMID 40013670, 2025). "Biologically, given that DIRAS2 plays a tumor suppressor role in pancreatic ductal adenocarcinoma (PDAC) induced by KrasG12D4, we hypothesized that USP10 would likely regulate the growth of pancreatic cancer cells via stabilizing DIRAS2." (PMID 39314885, 2024). "Collectively, these results indicate that patients with pancreatic cancer with high USP10 or N1ICD protein levels could potentially benefit from SAH-mAH2-5 treatment." (PMID 37714834, 2023). "USP10 is highly expressed in pancreatic cancer cell lines and positively correlated with LINC00460." (PMID 37786443, 2023). "Moreover, upregulation of USP10 in pancreatic cancer tissues, as well as in patient serum, was observed in several GEO datasets." (PMID 37714834, 2023). "In pancreatic cancer, miR-191 promoted pancreatic cancer development by targeting USP10." (PMID 37915040, 2023). "Additionally, USP10 is highly expressed in pancreatic cancer tissues and high expression of USP10 is closely related to poor prognosis in pancreatic cancer, including disease-free survival rates." (PMID 37786443, 2023). "Immunofluorescence analysis performed to verify this hypothesis revealed that N1DARP, N1ICD, and USP10 were co-localized in the cytoplasm of pancreatic cancer cells." (PMID 37714834, 2023). "Given that USP10 may be a tumor suppressor, several upstream regulators of USP10 including miR-191 and DZNep were identified in pancreatic cancer and thyroid cancer cells, separately." (PMID 35627217, 2022). "Our studies suggest that USP10 by protecting pancreatic cancer cells from ER stress may support tumor progression." (PMID 36543867, 2022). "Here we describe a tumor supportive role for USP10 in pancreatic cancer." (PMID 36543867, 2022). "Our results suggest that USP10 may be important for modulating recycling of ribosomal subunits and ER stress protection required to indulge the proteomic necessities of pancreatic cancer cells." (PMID 36543867, 2022). "We show that USP10 depletion inhibited cellular invasion in PDAC cells and decreased clonogenic ability, suggesting that silencing USP10 may decrease metastatic potential of pancreatic cancer." (PMID 36543867, 2022). "Next, we asked whether the protein folding capacity of pancreatic cancer cells was impaired after USP10 silencing even though global protein synthesis was unaffected." (PMID 36543867, 2022). "However, another study suggested that miR-191 promotes pancreatic cancer cell proliferation by inhibiting USP10 expression." (PMID 36248971, 2022). "Thus, silencing USP10 inhibits clonal growth and invasion in pancreatic cancer cell lines, two pivotal hallmarks of cancer progression." (PMID 36543867, 2022). "The role of USP10 in pancreatic cancer remains controversial." (PMID 36248971, 2022). "We next investigated the clinical relevance of USP10 expression in pancreatic cancer." (PMID 36543867, 2022).
pancreatic cancer (continued). "Interestingly, one recent study reports that microRNA-191 can promote pancreatic cancer progression by targeting USP10." (PMID 27003362, 2016). "Besides, several articles have indicated the roles of USP10 in pancreatic cancer." (PMID 36582601, 2022). "Thus, the specific regulatory role of USP10 in pancreatic cancer requires further investigation." (PMID 36248971, 2022). "Furthermore, it has been reported that miR-103 may also downregulate USP10 in pancreatic cancer cell lines and tissues." (PMID 36248971, 2022). "Overall, our studies suggest that USP10 may be a clinically relevant target in pancreatic cancer." (PMID 36543867, 2022). "KIF15 is responsible for USP10-induced PGK1 deubiquitination, thereby enhancing the glycolytic capacity for pancreatic tumor growth." (PMID 40087774, 2025). "KIF15 recruits USP10 to deubiquitinate and stabilise PGK1, amplifying glycolysis in pancreatic cancer." (PMID 41463025, 2025). "However, the role of USP10 in pancreatic cancer remains unclear." (PMID 36543867, 2022). "Additionally, N1DARP competitively inhibits the binding between N1ICD and USP10, promoting K11 and K48 ubiquitin-mediated degradation of N1ICD, which consequently suppresses the Notch signalling pathway and reduces pancreatic cancer stem cell properties." (PMID 41463025, 2025). "Likewise, in both PANC1 and Miapaca‐2 pancreatic cancer cells, USP10 overexpression increased DIRAS2 levels and inactivated pERK1/2 in a dose‐dependent manner (top left), whereas USP10 knockdown decreased DIRAS2 levels and activated pERK1/2 (top right)." (PMID 39314885, 2024). "On the other hand, USP10 deubiquitinated and stabilized YAP/TAZ to promote the proliferation of liver cancer cells, and by deubiquitinating PABPC1, USP10 increased CLK2 translation to promote the growth of pancreatic cancer cells." (PMID 39314885, 2024). "Taken together, these findings confirm that N1DARP acts as a tumor suppressor and chemosensitizer by regulating USP10-Notch1 oncogenic signaling, and suggest a promising therapeutic strategy targeting the N1DARP–N1ICD interaction in Notch1-activated pancreatic cancer." (PMID 37714834, 2023). "We first determined the expression levels of USP10 in different pancreatic cancer cell lines and in the non-malignant human pancreatic ductal epithelial cells (HPDEC) by immunoblotting." (PMID 36543867, 2022). "Interestingly, the K-Ras wild-type BxPC-3 cells also showed a ~32% decrease in clonal growth, suggesting that the impact of USP10 depletion in pancreatic cancer cells is independent of the K-Ras status." (PMID 36543867, 2022).
glioblastoma (14 papers, 2016 to 2025). The most malignant astrocytic tumor (WHO grade IV). "USP10 promotes pathological progression in Alzheimer's disease and glioblastoma on the one hand, and exerts protective effects in Parkinson's disease and ischemic stroke on the other." (PMID 41284210, 2025). "In glioblastoma, both Spautin-1 treatment and USP10/USP13 knockdown reduce cell proliferation and migration." (PMID 40370434, 2025). "Recent studies suggested the USP10/CCND1 pathway as a potential therapeutic target for glioblastoma (GBM) patients." (PMID 38953023, 2024). "Emerging evidence has reported that USP10 is dysfunctional in several human cancers, such as glioblastoma, and hepatocellular carcinoma." (PMID 34967276, 2022). "Conversely, USP10 is overexpressed in glioblastoma multiforme, prostate, and breast cancers." (PMID 36543867, 2022). "It was first shown that increased expression of USP10 predicted poor survival in patients with glioblastoma multiforme (GBM)." (PMID 35627217, 2022). "Previous studies have suggested that USP10 can promote Raf-1 protein expression and activate the Raf-1/MEK/ERK pathway in endometriosis and glioblastoma." (PMID 39430239, 2024).
colon cancer (13 papers, 2020 to 2023). "It was shown that dysregulated USP10 function promotes carcinogenesis via SIRT6 degradation in human colon cancer and the crosstalk between UPS10 and SIRT6 controls cell-cycle progression and proliferation." (PMID 38203666, 2023). "Here, we identify the DUB ubiquitin-specific protease 10 (USP10) as an important player in the control of colon cancer progression and a new modifier of the hypoxia response." (PMID 37371055, 2023). "Focus on drug resistance of cancer, there were also several studies that demonstrated that USP10 participated in cisplatin resistance of osteosarcoma cells, colon cancer cells, cervical cancer cells, and non-small cell lung cancer cells." (PMID 37919637, 2023). "This is exemplified in colon cancer where USP10 seems to have tumor-promoting functions or tumor-suppressive activities." (PMID 37371055, 2023). "For example, in colon cancer, USP10 interacted with and stabilized SIRT6 through inhibiting SIRT6’s ubiquitination, suppressing proliferation." (PMID 35627217, 2022). "For example, in colon cancer, USP10 interacted with and stabilized SIRT6 through suppressing SIRT6 ubiquitination." (PMID 35627217, 2022). "Recent studies on colon cancer cell lines have suggested that both USP10 and MSI2 proteins are upregulated." (PMID 32828126, 2020). "Mechanistically, we show that knockout of USP10 in different colon cancer cells causes an elevation in HIF-1α but not HIF-2α protein levels under both normoxic and hypoxic conditions." (PMID 37371055, 2023). "Overall, the data support the view that feedback cycles between the hypoxia response and DUBs exist and that USP10 can participate in carcinogenesis by modulating the hypoxia response pathway and regulating several aspects that are important for cellular growth in colon cancer cells." (PMID 37371055, 2023). "Moreover, USP10 could inhibit c-Myc transcriptional activation via stabilization of SIRT6 to inhibit tumor formation in colon cancer." (PMID 35277183, 2022). "The presented study aimed to further discover the role of USP10, a member of the DUB family, especially in colon cancer cells." (PMID 37371055, 2023). "Further, USP10 knockout increases cellular migration and adhesiveness via activation of HIF-1α signaling especially in colon cancer cells." (PMID 37371055, 2023). "Investigating the role of USP10 is essential to partly clarify the specificity and activity of DUB family members to develop DUB-targeting drugs in future colon cancer therapies." (PMID 37371055, 2023). "Furthermore, USP10 knockout in HCT116 and COLO320 colon cancer cells led to higher HIF-1α protein levels under both normoxia and hypoxia." (PMID 37371055, 2023). "Vice versa, we found that a lack of USP10 in different colon cancer cells promoted translation of HIF-1α via mTOR/S6K signaling and at the same time tumorigenesis." (PMID 37371055, 2023).